PELP1 (proline, glutamate and leucine rich protein 1)
Diseases named in the same sentence as PELP1 in open-access papers (continued):
Sharing a sentence is not in itself a finding about the gene and the disease.
tumor (continued). "PELP1 silencing by short hairpin RNA promoted the senescence and inhibited the proliferation, colony formation, migration, invasion, and xenograft tumor formation of the CRC cell line HT-29." (PMID 24967003, 2014). "PELP1 silencing by short hairpin RNA (shRNA) promoted the senescence and inhibited the proliferation, colony formation, migration, invasion, and xenograft tumor formation of the CRC cell line HT-29." (PMID 24967003, 2014). "PELP1 silencing by shRNA promoted the senescence and inhibited the proliferation, colony formation, migration, invasion, and xenograft tumor formation of CRC." (PMID 24967003, 2014). "Treatment of ERα-positive tumors with PELP1-siRNA-liposomes or pargyline significantly reduced tumor volume." (PMID 22812534, 2012). "PELP1-siRNA-DOPC treatment significantly decreased tumor cell proliferation and induced apoptosis compared with control siRNA-DOPC treatment." (PMID 22812534, 2012). "PELP1 deregulation correlates with increased aromatase expression resulting in tumor proliferation via local estrogen synthesis." (PMID 22812534, 2012). "In ECa, PELP1 expression is significantly higher in ECa tumor tissues compared to normal tissues." (PMID 41463382, 2025). "PELP1 is high in GCa cell lines and patient tumor samples compared to normal cells." (PMID 41463382, 2025). "Future efforts should focus on improving the pharmacokinetic properties and tumor selectivity of PELP1 inhibitors, such as SMIP34, and exploring combination strategies with endocrine therapy, CDK inhibitors, DNA damage response, or immunotherapy to overcome resistance mechanisms." (PMID 41463382, 2025). "PELP1 KD reduces OCa cell growth in vitro and tumor progression in vivo." (PMID 41463382, 2025). "PELP1 siRNA-loaded liposomes were efficient in reducing tumor growth of BCa and OCa." (PMID 41463382, 2025). "Additionally, PELP1 drives angiogenesis via the STAT3/VEGFA axis in endothelial cells, PELP1 KD significantly reducing tumor growth and angiogenesis in vivo." (PMID 41463382, 2025). "We next evaluated whether pharmacologic inhibition of PELP1 using SMIP34 resulted in a reduction of tumor growth." (PMID 39258975, 2024). "Through the use of the TNMplot analytic platform, which permits comparison of gene expression between tumor and normal tissues using established databases, we looked at whether PELP1 is overexpressed in ECa." (PMID 37853941, 2024). "Furthermore, the knockdown or pharmacologic inhibition of PELP1 significantly decelerated the HCC tumor growth in xenograft models." (PMID 39258975, 2024). "Furthermore, to verify the effect of PELP1 on tumor angiogenesis, the results showed that suppression of PELP1 significantly reduced MVD." (PMID 35053547, 2022). "Finally, we demonstrated that PELP1 plays a critical role in SETDB1 mediated tumor progression in vivo." (PMID 35395812, 2022). "Interestingly, knockdown of PELP1 in SETDB1 overexpression (MCF7-PELP1KD + SETDB1) xenografts resulted in significantly reduced tumor growth compared to MCF7-SETDB1 xenografts, suggesting that PELP1 KD effectively reduces SETDB1 mediated tumor progression." (PMID 35395812, 2022). "Taken together, these data suggest that PELP1 suppression could induce vascular normalization and then enhance chemotherapy efficiency by improving delivery of anti-tumor drugs into tumor tissues." (PMID 35053547, 2022). "The mean Q score for tumor cells showing PELP1 expression was found to be 101.54 (n = 13)." (PMID 34774800, 2022). "Of note, PELP1 suppression combined with chemotherapeuticdrug has a synergistic anti-tumor effect." (PMID 35053547, 2022). "In this study, we found a novel mechanism that PELP1 regulates tumor angiogenesis by promoting the expression of VEGFA, and may become a new target for anti-tumor angiogenesis therapy." (PMID 35053547, 2022). "Moreover, suppression of PELP1 reduced tumor growth and angiogenesis in vivo accompanied by inactivation of STAT3/VEGFA pathway." (PMID 35053547, 2022).
tumor (continued). "As a proto-oncogene, PELP1 promoted proliferation, migration, and invasion of multiple tumor cells." (PMID 34257530, 2021). "In LUAD tissues, PELP1 positive immunoreactivity was mainly located in the nuclei of tumor cells." (PMID 34257530, 2021). "Therefore, PELP1 overexpression was reported to induce malignant transformation of normal cells, accelerate cell cycle progression, promote tumor cell proliferation, and enhance migration and invasion of tumor cells." (PMID 34257530, 2021). "In addition, Box plots data further showed that the PELP1 level is correlated with tumor grades of GC patients closely." (PMID 32117782, 2019). "Furthermore, in vivo syngeneic tumor studies showed that PELP1 knockdown in a murine-derived MMTV-AIB1 tumor cell line increased the duration of survival for tumor-bearing mice." (PMID 30652114, 2018). "Finally, multivariate Cox analysis that included age, grade, gender, and ERβ, TIF2, AIB1, and PELP1 expression revealed that high ERβ expression along with lower tumor grade were independent favorable prognostic factors of overall survival." (PMID 29113424, 2017). "The expression of PELP1 in TNBC was compared to clinicopathological variables including patient’s age, tumor size, lymph node stage, tumor grade, clinical stage, histological type, Ki-67 LI, and primary treatment to see if there were correlations between PELP1 and these variables." (PMID 26472563, 2015). "Among postmenopausal women, PELP1 tumor levels correlated positively with estrone (E1) and estradiol (E2) levels in both normal tissue (r = 0.543, P = 0.003 and r = 0.601, P = 0.001, respectively) and plasma (r = 0.392, P = 0.053 and r = 0.403, P = 0.046, respectively)." (PMID 26247365, 2015). "Overall, the divergent results between these studies suggest that PELP1 may have different prognostic impact in settings of different tumors or possibly within different subgroups of the same tumor." (PMID 26472563, 2015). "Correlations of tumor PELP1 mRNA with estrogens in tumor, normal tissue and plasma." (PMID 26247365, 2015). "An intensive PELP1 staining within the nucleoli of the tumor cells can be observed." (PMID 23497172, 2013). "The expression of PELP1, ERalpha, and ERbeta was characterized in tumor tissues of 63 EOC patients." (PMID 23497172, 2013). "Finally, we demonstrated that PELP1 plays a critical role in HCC tumor progression in vivo." (PMID 39258975, 2024). "Thus, PELP1 could regulate tumor metastasis by controlling the expression and functions of the tumor metastasis suppressors miR-200a and miR-141." (PMID 36968022, 2023). "Therefore, we hypothesized that PELP1 suppression reduced the secretion of VEGFA to induce tumor vessel normalization." (PMID 35053547, 2022). "Finally, we showed that PELP1 plays a critical role in TPAP2C‐mediated tumor progression in vivo." (PMID 33269540, 2021). "Thus, based on these data, and the knowledge that PELP1 is an estrogen regulated gene, we hypothesize that the tumor PELP1 level is regulated by circulating estrogens." (PMID 26247365, 2015). "Compared with controls, mice treated with PELP1-siRNA-DOPC had a significant reduction in tumor volume by 58.6% (P < 0.001) without causing any observable signs of distress or changes in behavior, mobility or weight loss (data not shown), indicating low treatment toxicity." (PMID 22812534, 2012). "PELP1 signaling contributes to CRC progression by enhancing cell viability, clonogenicity, invasion, and tumor progression." (PMID 41463382, 2025). "We pinpointed 8 human-derived genes (PHF14, PELP1, RPL7L1, HPRT1, RELN, RNU1-75P, RNU5A-8P, RNVU1-19), likely to represent tumor-specific signals as a signature combining these genes demonstrated high accuracy in assessing therapy response." (PMID 39337470, 2024).
tumor (continued). "Hypoxia inducible factor (HIF) 1α/2α, glucocorticoid receptor (GR), and the phosphorylated S134-GR/PELP1/HIF signaling complex have been shown to induce the expression of PTK6, thus promoting the survival and metastasis of tumor cells." (PMID 37932734, 2023). "Previous reports have shown that PELP1 regulate the phosphorylation of STAT3 (p-STAT3), and STAT3 regulate the expression of VEGFA to affect the angiogenesis of tumor." (PMID 35053547, 2022). "It is worth noting that suppression of PELP1 reduces VEGF expression and secretion, and then enhances the efficacy of tumor chemotherapy via vascular normalization, which provides a novel target for anti-angiogenesis in CRC." (PMID 35053547, 2022). "In this study, we found for the first time that PELP1 was positively correlated with MVD in CRC and proved that PELP1 regulated tumor angiogenesis through the STAT3/VEGFA axis." (PMID 35053547, 2022). "Given the pivotal roles of VEGFA and PDGF-BB in tumor angiogenesis, we conducted ELISA assay on these two genes and found that only VEGFA is significantly down- and up-regulated by PELP1 depletion and overexpression, respectively." (PMID 35053547, 2022). "In this study, we examined PELP1 in 76 cases of LUAD and 17 non-tumor lung (NTL) tissues using IHC and correlated the PELP1 IHC scores with clinicopathological parameters of the patients of LUAD." (PMID 34257530, 2021). "PELP1 immunoreactivity in 76 cases of LUAD and 17 cases of non-tumor lung (NTL) tissues were examined." (PMID 34257530, 2021). "ERX-11 was potent (73% reduction in tumor volume compared to control) against the growth of MCF-7-PELP1 xenografts, which overexpress PELP1 (3-fold higher than parental MCF-7)." (PMID 28786813, 2017). "However, PELP1 has been suggested to be involved in both the nuclear-initiated and membrane-initiated action of estrogen, and earlier IHC studies performed at the MD Anderson Cancer Center also reported PELP1 to have extensive cytoplasmic location in a panel of tumor tissues." (PMID 26472563, 2015). "In the subgroup with tumor size ≤ 2 cm, patients with high PELP1 protein expression showed significantly shorter DFS compared with those with low PELP1 expression." (PMID 26472563, 2015). "PELP1 promotes tumor progression and metastasis, particularly in non-luminal subtypes (better than GATA3), and is associated with poor survival outcome." (PMID 41463382, 2025). "Our IHC study employing a TMA also showed that PELP1 was expressed more strongly in ECa tumor tissue than in normal endometrium." (PMID 37853941, 2024). "Moreover, tumor vascular normalization can reduce tissue hypoxia.To detect the hypoxic areas in tumor tissues, pimonidazole (PIMO) staining revealed that the hypoxic areas were significantly decreased in PELP1 knockdown tissues." (PMID 35053547, 2022). "It has been shown that PELP1 promotes tumor metastasis, but there is no report on the relationship between PELP1 and tumor vessels." (PMID 35053547, 2022). "We only aimed to assess if PELP1 was expressed in normal and tumor adrenal samples without indicating any difference in the expression levels since a limited number of samples were available." (PMID 29112114, 2017). "Moreover, we correlated PELP1 with the ER mRNA expression (ESR1) and estrogen levels in plasma, normal breast tissue and tumor tissue." (PMID 26247365, 2015). "PELP1 protein immunostaining was exclusively localized to the nuclei of tumor cells, with no cytoplasmic staining observed in any sample in this cohort." (PMID 26472563, 2015). "The independent effect of PELP1/ Ki-67 double high expression on DFS and OS was assessed using a multivariable Cox proportional hazards regression model, adjusted for patient age, tumor size, lymph node stage, tumor grade, and histological type." (PMID 26472563, 2015). "Similarly PELP1 which interacts directly with STAT3 and is responsible for cell proliferation and survival in several tumours, is likewise an identified drug target in PDAC." (PMID 25521701, 2014).
tumor (continued). "Conversely, absent or weak DACH1 nuclear staining represents unopposed PELP1 mediated tumour cell growth." (PMID 24392136, 2014). "High PELP1 expression is linked with greater invasion depth, lymph node metastasis, higher tumor histological grade, and advanced TNM stage, but not with age, sex, tumor size, or tumor number in lung cancer." (PMID 41463382, 2025). "Many reports have shown that the normalization of tumor vessels improve the efficacy of radiotherapy and immunotherapy, whether there is the same effect on the normalization of vessels induced by PELP1 is not clear in this study." (PMID 35053547, 2022). "In ER -negative breast cancer, deregulated PELP1 modulated the transcription of genes involved in epithelial-to-mesenchymal transition (EMT) and enhanced the activity of matrix metalloproteinases, thereby promoting tumor invasion and metastasis." (PMID 26472563, 2015).
infection (2 papers, 2019 to 2022). The state of being infected such as from the introduction of a foreign agent such as serum, vaccine, antigenic substance or organism. "As inflammation is a physiological response to either infection or tissue injury, we decided to investigate the induction of PELP1 during tissue damage." (PMID 34774800, 2022). "Knockdown of PELP1 or SENP3 was reported to decrease HSV-1 titers, and PELP1 was found enriched with chromatin during HSV-1 infection at 8 hpi relative to mock infection." (PMID 31337724, 2019).
PELP1 also shares sentences with these, for which no sentence is quoted: Adrenocortical Cancer (1 paper); bladder cancer (1); brain cancer (1); choroid plexus papilloma (1); esophageal cancer (1); ischaemic stroke (1); lung adenocarcinoma (1); lymph node metastasis (1); mucinous tumors (1); pancreatic ductal adenocarcinoma (1); periodontal disease (1); undifferentiated carcinoma (1).